CTLA4 (cytotoxic T-lymphocyte associated protein 4)
Diseases named in the same sentence as CTLA4 in open-access papers (continued):
Sharing a sentence is not in itself a finding about the gene and the disease.
melanoma (continued). "Anti-PD-1 and anti-PD-L1 antibodies also have fewer side effects than anti-CTLA-4 antibodies and are now authorized for the treatment of melanoma, lung carcinomas, renal carcinomas, bladder carcinomas, colon carcinomas, and Hodgkin lymphoma, amongst many other cancers." (PMID 39204136, 2024). "However, resistance to ICI therapies is relatively common, with 55% of melanoma patients presenting innate resistance to anti-PD-1; 40% to anti-PD-1/anti-CTLA-4 combination; and 25% patients developing resistance to anti-PD-1 within two years of treatment." (PMID 39491031, 2024). "However, high-CD44-expression patients exhibited an extended PFS compared with low-CD44-expression patients in Gide2019_PD1+CTLA4-Melanoma and Prat2017_PD1-NSCLC-HNSC-Melanoma cohorts." (PMID 38590654, 2024). "Ipilimumab as a CTLA4 blocker, it has been applied to the treatment of advanced melanoma." (PMID 38226966, 2024). "On the other hand, cirAEs may appear more frequently in one tumor type (e.g., melanoma) due to the more frequent use (and at higher doses) of CTLA-4 blockade in that tumor type." (PMID 38254829, 2024). "Furthermore, a preclinical study demonstrated that CTLA-4 and PD-1 ICI increased CD8 + T-cell intratumoral infiltration compared to anti-CTLA-4 monotherapy, increasing the rate of tumor-free survival in melanoma mouse models by ~ 65%." (PMID 38956700, 2024). "Especially, PD-1 and CTLA-4 blocking antibodies are widely used in clinical melanoma treatment." (PMID 38475660, 2024). "Also, in a study conducted on 48 patients with advanced melanoma, 35 patients received anti-PD-1 monotherapy, 11 received anti-PD-1 and anti-CTLA-4, and 2 received anti-CTLA-4 monotherapy." (PMID 39273452, 2024). "Adjuvant treatment with immune checkpoint inhibitors, such as PD1-antibodies (ICI) ± CTLA4-antibodies (cICI) or targeted therapy with BRAF/MEK inhibitors (TT), has shown a significant improvement in disease-free survival (DFS) for high-risk melanoma patients." (PMID 38743104, 2024). "However, the role of CTLA-4 has been extensively studied in various other malignancies, including lung, breast, gastric, colorectal, and malignant melanoma." (PMID 39286684, 2024). "Ipilimumab, a CTLA-4 inhibitor, has gained approval for treating advanced or incurable melanoma." (PMID 39328455, 2024). "Similarly, about 60%-70% of melanoma patients are unresponsive to anti-PD-1 monotherapy (nivolumab or pembrolizumab), and 40%-50% of patients are unresponsive to anti-CTLA-4 combination therapy." (PMID 38835779, 2024). "Thus, there has been increasing interest in a combined anti-PD-1/PD-L1 and anti-CTLA-4 checkpoint blockade for the treatment of melanoma." (PMID 38732242, 2024). "Indeed, there have been reports indicating that melanoma patients exhibiting a positive immune response to NY‐ESO‐1 showed favorable responses to anti‐CTLA‐4 therapy." (PMID 38455491, 2024). "While the here reported real-world evidence supports the high clinical efficacy of ICI in advanced melanoma patients, it also suggests that the combination of PD-1- and CTLA-4- blocking antibodies, are mostly beneficial for patients with metastatic disease affecting more than two organ systems." (PMID 39516682, 2024). "Excessive immune stimulation leading to adverse autoimmune events has previously been reported following anti–CTLA-4 treatment in melanoma patients, and therefore it is possible that the optimal therapeutic dose may vary between applications." (PMID 38226924, 2024). "Anti-CTLA4 is thought to be one of the best predictors of melanoma response." (PMID 39312339, 2024). "Importantly they identified a relationship between high levels of aneuploidy and poor response to CTLA4 inhibition in patients with melanoma." (PMID 39025846, 2024).
melanoma (continued). "Finally, in one of our clinical studies, we evaluated the safety and tolerability of combining an anti-TNF agent, either infliximab or certolizumab, with anti-CTLA-4 (ipilimumab) and anti-PD-1 (nivolumab) antibodies in advanced melanoma patients." (PMID 39136013, 2024). "Eligibility for the study was determined for patients who had advanced melanoma with progression on anti-PD-1/L1 antibody as their immediate preceding therapy, which could include combinations excluding anti-CTLA-4 antibodies." (PMID 39155358, 2024). "A cross-comparison study using survival data and safety profiles from two clinical trials was conducted to assess the impact of LAG-3/PD-1 inhibition (relatlimab–nivolumab therapy) versus CTLA-4/PD-1 inhibition (ipilimumab–nivolumab) in untreated advanced melanoma patients." (PMID 38318190, 2024). "The therapeutic success of targeting CTLA-4 with a human anti-CTLA-4 antibody for treating melanoma has been demonstrated, suggesting that blocking CTLA-4 may represent a promising new approach for cancer therapy." (PMID 39329742, 2024). "Many groups around the world have studied the approach of ICIs in melanomas; most approaches were successful, while in advanced-stage melanoma patients’ application of ICIs, monoclonal antibodies CTLA-4, PD-1, and PD-L1 have produced a good response (a median survival of 5 years)." (PMID 39195270, 2024). "Furthermore, separate research examined the immune profile and transcriptomics of 158 tumor samples obtained from advanced melanoma patients who received either anti-PD-1 monotherapy (n = 63) or a combination of anti-PD-1 and anti-CTLA-4 (n = 57)." (PMID 39273452, 2024). "In addition, the combination of ICIs such as dual anti-CTLA-4 and anti-PD-1 therapy has been shown to have improved outcomes, especially in patients with advanced melanoma." (PMID 39534873, 2024). "Also, flow cytometry from PBMCs isolated from 31 melanoma patients treated with anti-PD-1 or anti-PD-1 plus an anti-CTLA-4 combination revealed that responders showed an increase in the CD8+ Tem subset after three weeks of treatment." (PMID 39273452, 2024). "Loss of MHC-I expression in melanoma cells leads to resistance to anti-CTLA-4 but not anti-PD-1 therapy." (PMID 37877810, 2024). "Therefore, the CTLA4 downregulation observed in melanoma cell secretome-treated Treg cells was achieved through miRNA-mediated gene silencing at the post-transcriptional level." (PMID 37197667, 2023). "Precisely, MTHFR could act as blockbuster biomarker for ipilimumab to melanoma of anti-CTLA-4 ontreatment (AUC = 0.9, P < 0.0001) and potential cancer biomarker for nivolumab to melanoma of anti-PD-1 ontreatment (AUC = 0.712, P = 0.006)." (PMID 37354330, 2023). "As CTLA-4 inhibitors reduce the number and function of Tregs in malignant melanoma, the positivity of FoxP3 could help in the decision-making process between monotherapy with PD-1 inhibitors and combination therapy with PD-1 and CTLA-4 inhibitors." (PMID 36980787, 2023). "Ipilimumab is a CTLA-4-targeted monoclonal antibody which has applied in melanoma." (PMID 36895477, 2023). "Despite its potential as a treatment strategy for melanoma, CTLA-4 inhibition has limited efficacy." (PMID 37197667, 2023). "The authors of this report speculate that increased expression of EZH2 during melanoma immunotherapy with anti-CTLA-4 antibodies or IL-2 triggers diminution of therapy efficacy." (PMID 37325482, 2023). "Our study provides new insights into the underlying mechanisms of reduced CTLA4 expression observed in melanoma patients, demonstrating that post-transcriptional silencing of CTLA4 by miRNA-155 in Treg cells may play a critical role." (PMID 37197667, 2023). "To understand whether IL-17A is also a relevant contributor to CTLA-4 and PD-1 blockade in human melanomas, we used an ex vivo patient-derived tumor fragment (PDTF) model, which has recently demonstrated high predictive capacity for ICI22,23." (PMID 37525015, 2023).
melanoma (continued). "A phase I clinical trial of dual blockade of CTLA-4 (ipilimumab) plus VEGF (bevacizumab) showed increased tumor antigen recognition, tumor-associated endothelial activation, and infiltration of T cells in melanomas." (PMID 37138880, 2023). "Since the association of tumor CTLA4 expression with OS in melanoma patients has not been well characterized, we first analyzed this relationship in TCGA melanoma patients." (PMID 37197667, 2023). "One of the most significant findings of our study was that USP28 could serve as a significant predictor of anti-CTLA4 therapy response in melanoma patients." (PMID 37450415, 2023). "Further analysis showed that among these patients, not those with primary melanoma (n = 42) but those with metastatic melanoma (n = 244) had a significant association between low CTLA4 expression and worse OS (p = 0.0001)." (PMID 37197667, 2023). "While several reports suggest that particularly inflamed tumors respond better to ICI8, it is controversial whether TH17–IL-17 inflammation could have an anti-tumor effect in melanoma, particularly during combined anti-PD-1 and anti-CTLA-4 therapy." (PMID 37525015, 2023). "Studies have indicated that impairments in the IFN-γ signal pathway in melanoma could also lead to a reduced response to anti-CTLA-4 therapy." (PMID 38139110, 2023). "In patients with advanced melanoma, a high baseline proportion of terminally differentiated effector memory CD8 was negatively associated with OS upon anti–Cytotoxic T-Lymphocyte-Associated protein-4 (CTLA-4) treatment." (PMID 37939189, 2023). "In addition, the keyword “CTLA-4” is also a relatively popular checkpoint inhibition, which plays an important role in the immunotherapy of melanoma." (PMID 37427124, 2023). "Paired sc-RNA and sc-TCR-seq analysis of melanoma patient specimens demonstrated that clonal T cells in periphery are in a more activated cellular state (CCL5+GZMB+KLRG1+KLRK1+CX3CR1+) than their counterparts in TME (PD-1+LAG3+CTLA-4+TIM-3+TIGIT+)." (PMID 37881432, 2023). "Despite significantly improved outcomes with anti-CTLA-4 and anti-PD-1/PD-L1 therapies, approximately half of patients with advanced melanoma do not achieve a durable response and face a high risk of recurrence, for which treatment options are limited." (PMID 37459511, 2023). "Other clinical data concerning melanoma patients have provided evidence that the combination of radiotherapy with a dual-checkpoint blockade, including anti-CTLA-4 and anti-PD-L1 antibodies, could promote an immune response through distinct mechanisms." (PMID 37443821, 2023). "We have shown CTLA-4 protein expression in melanoma cells and a negative correlation between CTLA4 promoter methylation and CTLA4 mRNA expression in melanomas, therefore we hypothesized that CTLA-4 could also be expressed by HNSCC tumor cells." (PMID 37415208, 2023). "Therefore, we compared the expression profiles of the three clusters (Cluster1, Cluster2, and Cluster3) with another published melanoma cohort containing 47 patients who received PD1 inhibitor or CTLA-4 inhibitor using SubMap analysis." (PMID 36936935, 2023). "Abscopal response rates (ARRs) of 51-53% were further identified in small cohorts of patients with advanced melanoma who progressed an anti-CTLA-4 ICI (Ipilimumab) or an anti-PD-1 ICI (Nivolumab or Pembrolizumab) after they received intra- or extra-cranial hypofractionated RT." (PMID 37377970, 2023). "Importantly, “CD21lo” B cells are increased in patients with melanoma who are treated with anti-CTLA4 or anti-PD1 plus anti-CTLA4, and these cells were transcriptionally suggestive of ABCs." (PMID 37965337, 2023). "The study suggests that CTLA4 methylation could serve as a predictive biomarker for the response to anti-CTLA-4 immunotherapy in melanoma." (PMID 37835379, 2023). "Clinical data suggest that anti-PD-L1 treatment may elicit a more sustained response to patients with melanoma compared to CTLA-4 blockade." (PMID 37046762, 2023).
melanoma (continued). "The immunotherapy with antibodies against immune checkpoint proteins cytotoxic T cell antigen 4 (CTLA-4) and programmed death receptor 1/ligand (PD-1/PD-L1) has greatly extended the lives of many melanoma patients, however, about 70% of patients show disease progression within 5 years." (PMID 37325482, 2023). "In particular, a higher level of sPD‐L1 prior ICIs treatment (anti‐CTLA‐4/anti‐PD‐1 blockade), was more likely to suffer from progressive diseases and poorer clinical outcomes in different types of tumors, such as melanoma, NSCLC, breast cancer, and other solid tumors." (PMID 37799808, 2023). "Ipilimumab (Yervoy®, MDX010), an anti-CTLA-4 monoclonal antibody, was developed by the Medarex company in 1999 and has achieved remarkable results in numerous clinical studies into the treatment of patients with advanced melanoma." (PMID 36604694, 2023). "Combination of pharmacological inhibition and anti-CTLA-4 antibody led to rejection of established tumors and resistance to secondary challenge in mice after inoculation with melanoma cells, which was mainly achieved through restored CD8+ and CD4+ T cells activity." (PMID 38313431, 2023). "Despite significantly improved outcomes with anti-CTLA-4 and anti-PD-1/PD-L1 inhibitors, approximately half of patients with advanced melanoma will not achieve a durable response and face a high risk of recurrence and death." (PMID 37459511, 2023). "The dire situation was changed in 2011 when the U.S. Food and Drug Administration (FDA) approved ipilimumab, an anti-human CTLA-4 monoclonal antibody that successfully improved the survival of melanoma patients in phase III clinical trials, opening a new era of immunotherapy on ICBs." (PMID 36640142, 2023). "Following successful trials at extracranial sites, increased efficacy has been demonstrated in the brain from combined ICI with PD-1/CTLA-4 blockade with response rates approaching 50% in these selective cohorts of patients with melanoma BrM, with some patients achieving a complete response." (PMID 38567052, 2023). "Lastly, we found an inverse relationship between baseline and on-treatment levels of circulating LAG3 transcript-expressing CD8 memory T cells and response to combination PD-1 and CTLA-4 blockade in a clinical trial cohort of melanoma patients profiled by scRNAseq." (PMID 37795090, 2023). "We therefore postulated that domatinostat might synergize with anti-PD-1 ± anti-CTLA-4 in patients with stage III melanoma and a low IFN-γ score in their baseline tumor biopsy." (PMID 36920329, 2023). "A study has shown that increased CD8+ T cell trafficking contributes to the efficacy of anti-programmed death 1 (PD-1)/CTLA-4 therapy against melanoma metastasis and may represent an effective immunotherapeutic strategy." (PMID 37373286, 2023). "Phase 2 randomized controlled trials evaluating the safety of CTLA-4-targeted agents or (PD)-1 and (PD-L1)-targeted agents in patients with advanced melanoma did not suggest an increased risk of infection." (PMID 37046650, 2023). "Analyses performed on peripheral and tumor-resident ILCs from patients with solid cancers, including melanoma, detected variable levels of CTLA-4 expression on all ILC subsets, with tissue cells showing higher expression compared to that in the blood counterpart." (PMID 36765891, 2023). "Using qRT-PCR, we demonstrated the upregulation of PDL1 and CTLA4 in melanoma." (PMID 37189408, 2023). "Receiver Operating Characteristics (ROC) analyses show MTHFR could act as a potential biomarker in anti-PD-1 (nivolumab to melanoma) and anti-CTLA4 (ipilimumab to melanoma) group of ontreatment, in anti-PD-1 (pembrolizumab to melanoma) group of pretreatment." (PMID 37354330, 2023). "Male predominance may be because the CTLA-4 inhibitor ipilimumab is commonly used in the treatment of melanoma, and men have a higher incidence of melanoma than women." (PMID 37240574, 2023).
melanoma (continued). "Therefore, we analyzed plasma samples of 121 patients with melanoma treated at the Essen Department of Dermatology with either first-line dual ICI (anti-CTLA-4 plus anti-PD-1 antibodies, n = 70) or with first-line anti-PD-1 monotherapy (n = 51)." (PMID 37525015, 2023). "Since the development of anti-CTLA-4 blockade, mechanisms that would induce T-cell desertification in B16 melanoma models (albeit having significant TMB) were unknown." (PMID 37454231, 2023). "Specifically, the discovery of antibodies directed to immune checkpoint molecules such as programmed cell death protein 1 (PD-1) and cytotoxic T-lymphocyte-associated-protein 4 (CTLA-4), and, more recently, lymphocyte activation gene 3 (LAG-3), have drastically prolonged survival in melanoma." (PMID 37900283, 2023). "Additionally, ICIs targeting PD-1, PD-L1, or CTLA4 have enabled the possibility of long-term survival in patients with tumors such as melanoma, HCC, breast cancer, and colorectal cancer." (PMID 37153542, 2023). "Following the FDA approval of Ipilimumab (a CTLA-4 inhibitor) for advanced melanoma in 2011, ICIs quickly gained approval for treating various cancer types, as evidenced by several FDA-approved immune checkpoints such as PD-1 and its receptor PD-L1, CTLA-4, and LAG3." (PMID 37600822, 2023). "In melanoma, tumor-intrinsic active β-catenin signaling has been associated with the absence of type-1 DCs and effector CD8+ T cells in addition to resistance to anti-PD-L1 and anti-CTLA-4 therapy." (PMID 37443821, 2023). "In a single-arm phase II clinical study (NCT01302496), patients with stage III/IV malignant melanoma were treated with DCs, electroporated with TriMix, and mixed with multiple LAMP-1-fused melanoma-associated tumor mRNAs (TriMixDC-MEL), along with ipilimumab (IPI; CTLA-4 inhibitor) mAb." (PMID 37681880, 2023). "However, the use of CTLA-4 for UC has been limited even though it is approved for use in the treatment of other highly mutagenic cancers, such as melanoma, renal cell carcinoma (RCC), and non-small cell lung cancer (NSCLC)." (PMID 38201559, 2023). "Furthermore, it is known that anti-CTLA4 therapy increases T cell receptor (TCR) repertoire diversity among peripheral blood T cells of melanoma and prostate cancer patients." (PMID 36068918, 2023). "It is critically important to reduce death rates in melanoma patients who develop resistance to targeted therapy, and salvage therapies such as immunotherapy with inhibitors of cytotoxic T cell antigen 4 (CTLA-4) and programmed death 1 (PD-1) checkpoints are used in clinics." (PMID 37175614, 2023). "There are emerging data showing long-term disease control after re-challenging immunotherapy with CTLA-4 and PD-1 antibodies in patients whose tumors had progressed on single agent PD-1 blockade in melanoma, hepatocellular carcinoma, non-small cell lung cancer, and urothelial cancer." (PMID 37569431, 2023). "Moreover, the possible interaction between LAG-3 and other checkpoints, namely PD-1 and CTLA-4, holds significant promise in raising the bar and extending the landscape of melanoma immunotherapy." (PMID 37484526, 2023). "To study the effect of the systemic IL-17A level on the anti-tumor efficacy of ICI therapy in vivo, we used two syngeneic melanoma transplantation models with distinct genotypes and response profiles to experimentally administered anti-CTLA-4 and anti-PD-1 antibodies." (PMID 37525015, 2023). "Seventeen years since the first use of granulocyte-macrophage colony-stimulating factor (GM-CSF) tumour vaccine to unleash T-cell generation for anti-CTLA-4 blockade response in B16 melanomas, extensive pre-clinical research has been carried out to improve DCs immunogenic functions." (PMID 37454231, 2023).